ZNF680 (zinc finger protein 680)
Description:
May be involved in transcriptional regulation.
Synonyms: FLJ90430
Tractability: PROTAC: UniProt records ubiquitination sites on it; ubiquitination databases record sites on it.
Gene: Protein-coding gene on chromosome 7 (64,519,878 to 64,563,078, reverse strand). Ensembl gene ENSG00000173041.
Subcellular location: Nucleus
Subcellular location (Human Protein Atlas): Nucleoplasm
Pathways (Reactome):
Gene expression (Transcription): Generic Transcription Pathway; Regulation of endogenous retroelements by KRAB-ZFP proteins
Gene Ontology:
Molecular function: DNA-binding transcription factor activity, RNA polymerase II-specific; RNA polymerase II cis-regulatory region sequence-specific DNA binding
Biological process: regulation of DNA-templated transcription; regulation of transcription by RNA polymerase II
Cellular component: nucleus
Genetic constraint (gnomAD): Loss-of-function variants: 5 observed, 10.65 expected, observed/expected ratio (o/e) 0.47, 90% interval 0.24 to 0.99. The upper end of that interval is the gene's LOEUF score, 0.99, which puts it in group 4 of 6, group 1 being the genes least tolerant of losing a copy. Missense variants: 547 observed, 623.86 expected, observed/expected ratio (o/e) 0.88, 90% interval 0.82 to 0.94. Synonymous variants: 170 observed, 203.97 expected, observed/expected ratio (o/e) 0.83, 90% interval 0.74 to 0.95.
Homologues: Orthologues: chimpanzee ZNF680 (99% identical), macaque ZNF680 (97% identical). Paralogues in human: ZNF92 (73% identical), ZNF273 (72% identical), ZNF723 (71% identical), ZNF737 (69% identical), ZNF98 (69% identical), ZNF430 (68% identical), ZNF431 (68% identical), ZNF257 (67% identical), ZNF675 (67% identical), ZNF66 (66% identical), ZNF730 (66% identical), ZNF626 (65% identical), and 6 more.
Diseases named in the same sentence as ZNF680 in open-access papers:
ZNF680 is named in the same sentence as 2 diseases in open-access papers, as found by Europe PMC text mining. Sharing a sentence is not in itself a finding about the gene and the disease. The quoted sentences say what the papers report.
breast carcinoma (1 paper, 2024). "Knocking down or knocking out ZNF680 reduced REG3A expression, while its overexpression increased it in primary breast cancer cells." (PMID 38840145, 2024). "Additionally, enhanced binding between ZNF680 protein and the REG3A promoter was observed in breast cancer tissues and cells." (PMID 38840145, 2024).
cancer (2 papers, 2020 to 2024). A tumor composed of atypical neoplastic, often pleomorphic cells that invade other tissues. "However, there are no any reports or laboratory data on the relationship between cancer and the following genes: GSG1L, CRB1, XKR8, ZNF680, ZNF284, and ZNF780B, which is part of the 17-gene signature." (PMID 32596394, 2020). "The other six genes (GSG1 like (GSG1L), crumbs cell polarity complex component 1 (CRB1), XK-related 8 (XKR8), zinc finger protein 680 (ZNF680), zinc finger protein 284 (ZNF284), and zinc finger protein 780B (ZNF780B)) are not mentioned in the cancer research area until now." (PMID 32596394, 2020).